RPEL1 (ribulose-5-phosphate-3-epimerase like 1)
Description:
Catalyzes the reversible epimerization of D-ribulose 5-phosphate to D-xylulose 5-phosphate.
Tractability: Antibody: the Human Protein Atlas places it where antibodies can reach. PROTAC: ubiquitination databases record sites on it.
Gene: Protein-coding gene on chromosome 10 (103,245,887 to 103,248,016, forward strand). Ensembl gene ENSG00000235376.
Subcellular location (Human Protein Atlas): Cytosol; Nucleoplasm; Plasma membrane
Pathways (Reactome):
Metabolism: Pentose phosphate pathway
Gene Ontology:
Molecular function: D-ribulose-phosphate 3-epimerase activity; metal ion binding; racemase and epimerase activity, acting on carbohydrates and derivatives
Biological process: carbohydrate metabolic process; pentose-phosphate shunt, non-oxidative branch; pentose-phosphate shunt
Cellular component: cytosol
Genetic constraint (gnomAD): Loss-of-function variants: 7 observed, 13.64 expected, observed/expected ratio (o/e) 0.51, 90% interval 0.29 to 0.96. The upper end of that interval is the gene's LOEUF score, 0.96, which puts it in group 4 of 6, group 1 being the genes least tolerant of losing a copy. Missense variants: 237 observed, 299.81 expected, observed/expected ratio (o/e) 0.79, 90% interval 0.71 to 0.88. Synonymous variants: 91 observed, 106.63 expected, observed/expected ratio (o/e) 0.85, 90% interval 0.72 to 1.02.
Homologues: Orthologues: macaque RPE (96% identical), guinea pig Rpe (94% identical), mouse Rpe (93% identical), rat Rpe (93% identical), tropical clawed frog rpe (86% identical), chimpanzee RPE (85% identical), dog RPE (80% identical), zebrafish rpe (79% identical), Caenorhabditis elegans F08F8.7 (56% identical), Drosophila melanogaster Rpe (56% identical). Paralogues in human: RPE (96% identical).
Diseases named in the same sentence as RPEL1 in open-access papers:
RPEL1 is named in the same sentence as 1 disease in open-access papers, as found by Europe PMC text mining. Sharing a sentence is not in itself a finding about the gene and the disease.
RPEL1 shares sentences with these, for which no sentence is quoted: rhabdoid tumor (1 paper).